IL2 (interleukin 2)
Diseases named in the same sentence as IL2 in open-access papers (continued):
Sharing a sentence is not in itself a finding about the gene and the disease.
tumor (continued). "For example, Th1 can influence APC antigen processing and also secrete chemokines including IL-2 and IFN-γ to recruit CTLs and NK to exert a local anti-tumor effect and to stimulate DC cells." (PMID 34692696, 2021). "Tao and his colleagues reported that effector B cells directly killed tumor cells via the Fas/FasL and CXCR4/CXCL12 pathways, and the killing activities can be improved by IL-2 and inhibited by IL-10." (PMID 34118931, 2021). "Among the immunotherapies tested, IFNα was more effective than anti-PD-L1, anti-CTLA-4, anti-4-1BB, IL-2, and IL-9 in reducing Myc-CaP CRPC tumor growth." (PMID 34771735, 2021). "To further investigate the effect of hIL15-ABD and anti-PD-L1 combination on tumor microenvironment, we determined the function of CD8+ T cells by observing activation of intracellular IFN-γ and IL-2." (PMID 33918641, 2021). "Future studies should investigate the anti-tumor properties of AnnV-IL2 and evaluate efficacy compared to conventional IL-2 therapy." (PMID 34804041, 2021). "Various immunocytokines have been combined with additional unconjugated cytokines such as IL-7, IL-2, Fms-like tyrosine kinase-3-ligand (Flt3-L), and IFN-γ to show enhanced tumor control and the activation of the immune response." (PMID 33803078, 2021). "There is a significant decrease of CD8+/CD4+T cells ratio, NK cells, IL-2, and IFN-γ and a significant increase of T regs, IL-6, IL-1β, TNF-α, IL-10, and PGE2 in CUMS group, indicating the inhibition of immunity in the tumor microenvironment." (PMID 34422050, 2021). "These investigations, therefore, illustrate that via IL-2 and 4-1BB receptors combined stimulation enhances pE7-induced Ag-specific CD8+ CTL responses that increased the rates of tumor treatment and prolonged antitumor immune memory." (PMID 34267616, 2021). "On the other hand, ProIL2 “passively” targets MMPs that are secreted by tumor cells or are attached to inflammatory cells in the TME, thus decreasing the concern of endocytosis prior to IL-2 activation of CTLs." (PMID 33986267, 2021). "After 28 days, the mice receiving the IL‐2 and anti‐CTLA4 Ab‐loaded aAPCs demonstrated significantly smaller tumor size as well as increased survival, compared to the groups being treated with IL‐2 or anti‐CTLA4 Ab‐loaded aAPCs." (PMID 33898169, 2021). "With our functional in vitro studies, we demonstrated that in the presence of immobilized target antigens, CAR T products rich in effector memory T cells secreted higher amounts of IFNγ and IL-2, and induced more potent CAR-specific anti-tumor activity." (PMID 34503109, 2021). "We therefore measured IFN-γ and IL-2 production by PBMC and UC-3 tumor cells in the presence of VAR2, V-aCD3, aCD3 and a commercially available anti-CD3 monoclonal antibody (OKT3)." (PMID 33824272, 2021). "Tumor-infiltrating T cells in Bcl9-shRNA compared to NT-shRNA bearing tumors exhibited pathways enriched for TLR, FOXP3, and IL-2." (PMID 34417435, 2021). "Targeting HDAC1/2 inhibits the binding of CoREST with IL-2 and the IFN-γ promoter, thereby promoting their expression, inhibiting the function of Treg, and enhancing anti-tumor immunity." (PMID 34880761, 2021). "This revealed that pathways related to IL-2, CD4+ T cell memory formation and stimulation of CD8+ T were enriched in tumor-infiltrating T cells treated with hsBCL9CT-24." (PMID 34417435, 2021). "For this, we co-cultured IL-2-activated NK cells, isolated from two healthy donors, with untreated and MHT-treated U87 spheroids, and quantified tumor cell killing and the levels of CD107a in NK cells." (PMID 34683961, 2021). "In a xenografts mouse model, GD2-expressing ES combination of adoptively transferred Vδ2+ T cells expanded in vitro with zoledronic acid and IL-2, with anti-GD2 antibody ch14.18/ CHO, and with systemic zoledronic acid, significantly suppressed tumor growth." (PMID 33572900, 2021).
tumor (continued). "In contrast, in the syngeneic tumor cell engraftment system, elevated cytokine expression of IL-1β, IL-6, IL-2 and IFN-γ in GABARAP KO immune cells probably inhibited tumor cell growth." (PMID 34502326, 2021). "This product, which resulted in DCs secreting IL2 and TNF-α, was found to be safe and also yielded a reduction in tumor size." (PMID 33996630, 2021). "Immunotherapy with interleukin-2 (IL-2) and/or interferon alpha (IFN-α) was thought to increase and mobilize tumor-infiltrating lymphocytes (TILs), facilitating tumor regression." (PMID 33646368, 2021). "Effector CD8+ T cells in the tumor microenvironment generate Interleukin-2 (IL-2), IL-12 and Interferon-γ (IFN-γ), which enhance CD8+ CTLs, leading to targeted tumor cell killing." (PMID 35095898, 2021). "Highly aggressive, membrane Hsp70 positive tumor cells can be recognized and killed by Hsp70 peptide TKD and IL-2 (TKD/IL-2) stimulated NK cells in vitro and in vivo." (PMID 33559835, 2021). "During interaction between tumor cells and ATC, several pro-inflammatory cytokines (IFNγ, TNF-α, IL-4, and IL-2) are released in the tumor microenvironment resulting in immunomodulation of the tumor cells, with upregulation of PD-L1expression on their surface." (PMID 34689789, 2021). "Mechanistically, mid- and high-dose RHWPs were found to collectively promote the anti-tumor immune response by increasing TNF-α, IFN-γ, and IL-2 secretion; T and B cell proliferation; and NK and macrophage effector functions." (PMID 33921554, 2021). "Next, we focused on the IL-2/STAT5 signaling pathway, which plays important roles in both the stability of Foxp3 expression and the expansion of Foxp3+ Tregs even in the tumor microenvironment." (PMID 34248973, 2021). "Tumor cells from EPN exhibited an enrichment of the mTORC1 signaling pathway, while tumor cells from AEP showed a significant enrichment of the TGF-β, IL2/STAT5, and Hedgehog signaling pathways." (PMID 34824203, 2021). "IL-2/α-CD40 combination therapy has enough potential to induce the IFN-α– and NO-dependent reduction of MMP9 expression in the tumor microenvironment and diminishes the probability of metastasis development to the lung." (PMID 32902664, 2021). "T cells from tumor-bearing mice immunized with VP1/CA or VP1/RA shown increased secretion of IL-2, IFN-γ, and TNF-α than T cells from untreated tumor-bearing mice in this study, which were correlated with in vivo antitumor effects induced by VP1/CA or VP1/RA." (PMID 34611173, 2021). "Though low levels were detectable in mice followed after adoptive transfer for several days, the presence of a targetable tumor, the lymphodepletion regimen, injected CAR T cell numbers, and doses of IL-2 would influence CAR T cell clearance over time." (PMID 34806651, 2021). "Results of GSEA showed that pathways related to tumor progression (MAPK and FGFR), immunomodulation, and IL-2 synthesis inhibition were significantly downregulated in the FSIP2-MT group." (PMID 34113648, 2021). "We further explored immunologic signatures pathway and revealed that immunologic gene such as IL-2 and STAT1 was enriched in tumor cells." (PMID 34026600, 2021). "Compared to healthy individuals, the NPC patients exhibited elevated levels of IL-1β, IL-2 and IL-10, which is in accordance with previous findings in patients with NPC and in tumor-bearing rodent models." (PMID 34900691, 2021). "In HSC4-bearing huNOG-FcγR−/− mice, nivolumab induced both infiltration of T cells into tumor and increases of T-cell subpopulations expressing various cytokines or cytotoxic molecules, which include GZMB, IL-2, or IFN-γ." (PMID 34702924, 2021). "Recent research involving the treatment of NK cells with IL-2/HSP70 stimulated BBB crossing and the subsequent antitumor effects of NK cells and resulted in a substantial tumor growth inhibition and prolonged survival in an in vivo study." (PMID 35011678, 2021).
tumor (continued). "In the tested in vitro system, maximum tumor cytotoxicity (IC99) was reached at a concentration of 155 pM cibisatamab, which approximately corresponds to the EC5 for IL2 and IL6 release." (PMID 34862519, 2021). "Expressions of IL-2 and IL-2 receptor by CD8+ cytotoxic T lymphocytes (CTLs) and tumor-infiltrating lymphocytes (TILs) were also reduced under the influence of PGE2, while PGE2 induced CD4+ Th2 cell activation." (PMID 34497832, 2021). "Tumor-associated lineage−CD45+CD33+ MDSCs from high-grade ovarian serous cancer patients suppress proliferation of T cells and inhibit their function through downregulating the expression of IL-2, INF-γ, and granzyme B, resulting in increased tumor volume." (PMID 34359674, 2021). "Another study showed that IL-2 combined with TNFSF14 results in an increase in CD8+ central memory cells and a decrease in tumor size in preclinical exploration." (PMID 34721435, 2021). "Studies have shown that a combination of IL-2 and AKK exerts a strong anti-tumor effect on tumor tissues from colorectal cancer patients." (PMID 34745119, 2021). "NKT cell activation triggers a prompt release of an array of cytokines, including IL-2, IFN-γ, TNF-α, and IL-4, which modulate different immune cells present in the TME, thus affecting anti-tumor immune responses." (PMID 33802203, 2021). "IL-2 is a key regulator in immune system, which can induce the production of interferon-γ (IFN-γ) contributing to the virus and tumor therapy through cellular immunity." (PMID 34635698, 2021). "An immunohistochemistry (IHC) assessment of IL-2, IFN-γ and TGF-β expression in tumor tissues showed a consistent result with ELISA analysis." (PMID 34959271, 2021). "Shenling Baizhu powder increased the expression levels of IL-2, Interferon-γ (IFN-γ), and tumor necrosis factor-α (TNF-α) cytokines in the peripheral blood of tumor-bearing mice." (PMID 34803677, 2021). "Consistent with the exhausted phenotype displayed by the tumor-specific TILs, IFN-γ+ TNFα+ IL-2+ tumor-specific T cells were undetectable in MC38 tumors, and on average made up only 15% of tumor-specific T cells isolated from B16.F10 tumors." (PMID 34867942, 2021). "Generally, cytotoxic CD8+-T cells are antigen-processed and have ability to eliminate tumor cells, whereas CD4+ T helper 1 cells (Th1) activate cytotoxic T cells to secrete interleukin-2 (IL2), interferon gamma (IFNγ), and tumor necrosis factor." (PMID 34434889, 2021). "IN_in_r1 induces a preferable profile of immune response rich in IFN-γ/TNF-α/IL-2 and IFN-γ/IL-2/GrB producing CD8+ T cells, and IFN-γ/TNF-α and IFN-γ/IL-2/TNF-α producing CD4+ T cells, allowing better control of tumor cell challenge." (PMID 34199989, 2021). "IL-2 production by tumor-infiltrating CD8+ T cells is related to antitumor immunity, and IL-2 produced by CD8+ T cells can stimulate Tregs." (PMID 33777049, 2021). "Low concentrations of IL-2 have been shown to promote Treg function in the TME, whereby anti-tumor therapies that employ high dose IL-2 attempt to overcome this immunosuppressive role." (PMID 34012451, 2021). "Upon intratumoral injection, these AAA-CD4+ T cells underwent a dramatic expansion in the tumor and secreted high levels of IFN-γ and IL-2." (PMID 34625113, 2021). "Bispecific CAR T cells demonstrated a better anti-tumor activity and higher in vitro activation, with increased IFN-γ and IL-2 secretion, and improved cytolytic activity." (PMID 33746981, 2021). "Considering the functions of IL12, IL2, and GMCSF in the immune system, it can be envisaged that a positive feedback loop plays a pivotal role in fusion protein mediated tumor elimination." (PMID 34766145, 2021).
tumor (continued). "Reassuringly, we also detected increases in IL-2, and IFN-γ, with attendant survival benefits in tumor-bearing mice." (PMID 33936101, 2021). "IL-2 can activate nature killer (NK) cells to secrete CCL28, thus enhancing the targeted killing of tumor cells." (PMID 34307161, 2021). "To further investigate the effects of VES on inflammatory factors in tumour-bearing mice, we examined TNF-α, IL-12, IFN-γ, IL-2 and IL-10 in the spleen by use of qRT-PCR assays." (PMID 34093795, 2021). "IL-2, IL-4, IL-8, IL-22, IL-23, and TNF-α all exert a frank pro-tumoral activity in CLL by stimulating STAT and NF-κB transcription factors and enhancing tumor cell proliferation." (PMID 34944921, 2021). "An experimental study used KM2812 as an IL-2 construction and observed that following treatment of mice in some animals, complete regression occurred, and KM2812 had a considerable anti-tumor effect." (PMID 34868907, 2021). "This is an IL-2 dependent NK cell line, originating in patients with NHL, which requires their irradiation before infusion to the patient to avoid allogeneic tumor engraftment." (PMID 34066067, 2021). "Immune modulating cytokines (TGF-β, IL-10, IL-17, and IL-23) facilitate tumor development, while others (IFN-γ, TNF-α, GM-CSF, IL-2, IL-6, IL-17, and IL-12) promote immune surveillance and delay its growth." (PMID 34518597, 2021). "To confirm the finding of different IL2 expression in the groups of CSF1R c.1085 genotype A_A and A_G, we used anti-IL-2 specific antibody to stain IL-2 in CRC tumor samples." (PMID 34830445, 2021). "It is found that compared to ACT + IL-2, cells treated with ACT + NKTR-214 in vivo show increased polyfunctionality in spleen and tumor by 1.7-fold and 10-fold, respectively." (PMID 34000441, 2021). "NK cells pre-stimulated with IL-2 and TKD in combination with anti-PD-1 antibody improves cytolytic activity of NK cells against tumor cells and inhibits tumor growth in vivo." (PMID 34917098, 2021). "Earlier, same research team demonstrated that NK cells activated with IL-2 and TKD and combined with anti-PD-1 antibody increased cytolytic activity of NK cells toward cancer cells and delayed tumor growth in vivo." (PMID 33815422, 2021). "One recent study showed that combined treatment with IL-2 and Akkermansia muciniphila leads to stronger antitumor efficacy in CRC patient-derived tumor tissue and proposed this novel therapeutic strategy with prospecting application in the future." (PMID 34721435, 2021). "Our GSEA of TCGA-SKCM data also indicated that pathways related to tumor progression (MAPK and FGFR), immunomodulation, and IL-2 synthesis inhibition were significantly downregulated in the FSIP2-MT group." (PMID 34113648, 2021). "By contrast, when mice were treated with donor IL-2 NK cells isolated from RAG-1 KO mice that lack the expression of the KIR2DL3 inhibitory receptor, half of them were still alive 70 days after tumor injection." (PMID 34071607, 2021). "An enhanced therapeutic effect of F8-IL2 (an antibody-IL2 fusion protein) bombinated with anti-PD-1, anti-PD-L1 and anti-CTLA-4 antibodies was observed in immunocompetent mice bearing CT26 tumours." (PMID 33763344, 2021). "IL-2 and IFNγ (Interferon) producing CD4 T cells such as Th1 have been shown to play an essential role in the induction and persistence of anti-tumor CD8 T cells." (PMID 33498483, 2021). "M1 generates reactive oxygen species (ROS) and pro-inflammatory cytokines, such as IL-2, IFN-γ, TNF-α, and IL-1β, which play essential roles in killing tumor cells." (PMID 34721026, 2021). "A high level of IL2, IL2RA, and IL2RB gene expression and their relationships with tumor progression and malignancy have been previously reported." (PMID 33672900, 2021). "The treatment of tumor-bearing mice with SCPP11 increased the thymus index and the levels of both IL-2 and TNF-α in the serum." (PMID 34203182, 2021).
tumor (continued). "Studies have shown that interleukin-2 (IL-2) and the downstream transcription factor STAT5 are essential for maintaining regulatory T (Treg) cell homeostasis and function, suggesting that the immune microenvironment in tumor tissue of PAAD patients affected by somatic mutations may be disrupted." (PMID 34567094, 2021). "Other researchers have demonstrated that local administration of IL-2 increases the percentage of Th17 producing IFN-γ and TNF-α among tumor-infiltrating lymphocytes and induces the conversion of Tregs to Th17." (PMID 32148497, 2020). "Specific immune response was manifested by coproduction of IFN-γ/IL-2/TNF-α characteristic to the effector CD8+ and CD4+ T cells, which can eliminate tumor cells." (PMID 32570805, 2020). "Recently, we and others have demonstrated that combination therapy (CT) with co-administration of IL-2 and TGF-β neutralization in tumor-bearing mice results in the expansion of NK and CD8 T cells and consequently enhanced anti-tumor responses." (PMID 33138229, 2020). "Conjugating IL-2 to liposomes is inclined to target adoptive cell therapy (ACT) cells and induce ACT-T cell proliferation in tumor-tolerant mice, proving the feasibility of repetitive functional targeting of T cells in vivo." (PMID 33408716, 2020). "Recent studies have reported that elevation of TNF-α and IL-2 in tissues by transfecting oncolytic adenovirus loaded with TNF-α and IL-2 sequence into T cells modulates host tumor immune status and orchestrates TAMs toward the M1 type." (PMID 33505964, 2020). "We assessed the expression and activation of IL-2 signaling pathway components in CD4+ TILs and dLN cells in the MCA205 tumor model." (PMID 31924474, 2020). "In the context of supporting immune cell persistence in the immunosuppressive tumor microenvironment (TME), IL-2 and IL-15 have different potency in terms of regulating signaling pathway and protein synthesis." (PMID 33266177, 2020). "PD-L1-CAR T cells also demonstrated antigen-specific production of cytokines IL-2, IFN-γ, and TNF-α when incubated with PD-L1high tumor cell lines HCC827 and H1975 in vitro." (PMID 32792499, 2020). "By secreting IL-2, Th1 cells enable the proliferation and expansion of memory CD8+ CTLs required for tumor-cell lysis." (PMID 32104586, 2020). "Concentrations of IL-2, IL-13 and CCL5 in the irradiated tumor were similarly decreased by DEX treatment." (PMID 32325715, 2020). "Upregulated serum IL-2 and TNF-α levels and increased CD69 expression on the surface of tumor cells were also observed, which correlated with enhanced adaptive immunity." (PMID 32595757, 2020). "We performed H&E staining to verify tumor tissues and immunohistochemistry to detect the expression of OTUD7B, TRAF3, NIK, Ki67, MMP9 and IL-2 in the xenografted tissues." (PMID 33198776, 2020). "So far, CD56+ γδT cells and their functions have mainly been investigated in the aspect of anti-tumor activity, as CD56+ γδT cells show much stronger cytotoxicity following stimulation with IL-2 and IL-12 than CD56− γδT cells." (PMID 33603738, 2020). "IL-2 is a central cytokine for survival and proliferation of T cells qualifying TILT-123 to augment the transfer of tumor infiltrating lymphocytes (TIL)." (PMID 33202717, 2020). "For example, IL-2-engineered TILs displayed up to 10-fold enhanced proliferation and retention of CD8 T cells and NK cells in the tumor microenvironment (TME) with a minimal effect on Tregs." (PMID 32764348, 2020). "Glucocorticoids extensively modify cytokine signaling and inhibit the IL-2 and INF-γ pathways, which are reactivated to create the inflammatory tumor microenvironment during ICI therapy." (PMID 32306958, 2020). "In this study, in the orthotopic-mice model of HCC, YPF increased the levels of Th1 cytokines (IL-2, IL-12, TNF-α, and IFN-γ), decreased the levels of Th2 cytokines (IL-4, IL-5, IL-10, and IL-13), and increased the Th1/Th2 ratio in tumor and adjacent tissues." (PMID 32351590, 2020).